STAT1 (signal transducer and activator of transcription 1)
Diseases named in the same sentence as STAT1 in open-access papers (continued):
Sharing a sentence is not in itself a finding about the gene and the disease.
viral infection (continued). "Recently, it has also been shown that early activation of STAT1 during the viral infection is mediated by spleen tyrosine kinase (Syk) but not cytokine-activated JAK, providing new insights into the complex mechanisms underlying interaction between virus and host immune system." (PMID 36148221, 2022). "In the context of viral infection, human hepatic CSCs (Huh7, JFH-1-Huh7, Huh7.5, and MH14C) treated with BIO and infected with HCV suffered an impairment of IFN signaling via inhibition of signal transducer and activator of transcription 1 (STAT1) phosphorylation and degradation." (PMID 34017345, 2021). "The antagonism between STAT1 and STAT3 seems to be cell type-specific or specific to a certain gene locus, as a cooperation between STAT1 and STAT3 downstream of IL-6 has been described for optimal Bcl6 induction and Tfh differentiation in response to viral infections." (PMID 31998303, 2019). "Likewise, STAT1 KO U3C cells, which also have low levels of STAT2, lack this positive feedback system and are unresponsive to IFN treatment and unable to protect against viral infection." (PMID 29892288, 2018). "The significant downregulation of interferon signature genes, such as Adar (DRADA), Ddx58 (RIG-I), Ddx60 (DDX60), Stat1 (STAT1), Ifih1 (MDA5), Trim25 (TRIM25), Irf7 (IRF7), and Irf9 (IRF9) in infected Cd47−/− NK cells is consistent with the impaired Cd47−/− NK cell response to viral infection." (PMID 30643501, 2018). "Once again C6 associated with STAT2 and not STAT1, whilst N1 did not associate with either protein, confirming the specific interaction between STAT2 and C6 at endogenous protein levels during viral infection." (PMID 27907166, 2016). "Moreover, cells from STAT1 deficient (STAT1−/−) mice do not respond to IFN-γ stimulation leading to enhanced susceptibility to bacterial and viral infections." (PMID 23536884, 2013). "Taken together our data demonstrate that viral infection is exacerbated due to the reduced ability of Cav-1b morphant embryos to clear the infection resulting from the dispersal of CRFB1 and subsequent decrease in Stat1 gene expression, ISRE activation, and MxA induction." (PMID 23874753, 2013). "To get insight into the role of STAT1 in response to cytokines and viruses in salmon we have studied the expression and activation of STAT1 in primary leukocyte cultures and in different salmonid cell-lines upon type I and type II IFN treatment and viral infections." (PMID 20353564, 2010). "In addition, we noticed that viral infection can also upregulate linear ubiquitination of STAT1-Y701F, which is consistent with our above analysis, demonstrating that the Tyr701 residue is not required for STAT1 linear ubiquitination." (PMID 32123171, 2020). "Furthermore, YY1 interacts also in the absence of viral infection in mice with the signal transducer and activator of transcription 1 (STAT1), one of the main factors mediating ISG expression, implying important roles of YY proteins at different stages during infection." (PMID 32645843, 2020). "In addition, target cell killing by NK cells during viral infection was poor in the absence of STAT1, suggesting that Type I IFNs and STAT1 are important for NK cytolytic activity; however, the mechanism of this relationship remains unclear." (PMID 23300570, 2012). "Interestingly, the higher expression of genes of the IFN pathway like the transcription factors STAT1 and IRF7 as well as PKR, and IFN-β in IFN-DC resembles the expression pattern of plasmacytoid DC that are the major type I IFN producers during viral infections." (PMID 17894866, 2007). "To explore the potential role of USP12 in antiviral immunity, we first detected the expression of USP12 after virus infection and found that USP12 expression was induced by HSV-1 infection, which was mainly regulated by NF-κB p65 and IRF3, but not by STAT1." (PMID 37410794, 2023).
viral infection (continued). "Although such a negative regulation of IFN-γ by type I IFN has been observed during viral infection in an IFNAR- and STAT1-dependent manner, this has never been described in the context of TLR7/8-adjuvanted vaccines." (PMID 33262759, 2020). "A previous study has shown that cells lacking IRF3 are unable to produce type I IFN in viral infections and that TBK1 and IKK-I control both IRF3 and STAT1." (PMID 25942440, 2015). "To further dissect the response of monocytes to IFNα, we first monitored the phosphorylation of STAT1 and STAT2 in response to single or dual IFNα stimulation in the absence of viral infection." (PMID 20689596, 2010). "Mice lacking STAT1 exhibited normal birth rates and no obvious developmental abnormalities, but they developed severe issues with their IFN-dependent immunological responses to viral infections." (PMID 38994355, 2024). "The phosphorylation level of STAT1 (mediated by SeV-induced IFN response) was not affected by A3B expression, suggesting that A3B specifically regulates the PKR signaling pathway during viral infection." (PMID 36781883, 2023). "Moreover, the low number of CDV-infected cells expressing STAT1, STAT2 and MX indicates that the expression of these type I IFN pathway members is not directly induced by virus infection." (PMID 30939763, 2019). "Overexpression studies suggest that IFN responses are amplified by RIG-I, in the absence of viral infection, via direct interaction of the RIG-I CARD region with the STAT1 SH2-transactivation domain, impeding STAT1 dephosphorylation and thereby sustaining its activation." (PMID 30538296, 2019). "Additionally, STAT2-dependency, but not that of STAT1, was shown by IRF7 expression during viral infection." (PMID 25564224, 2015). "Indeed, in LNCaP-JAK1 cells, IFNγ activated STAT1 but not STAT3, abrogated NS3 production in EHDV-TAU-infected cells, and supported oncolysis by non-productive viral infection." (PMID 29441069, 2018). "Interestingly, unlike with STAT1 phosphorylation, we observed a comparable level of IFNAR1 between 54Stop-infected cells and uninfected cells, indicating that ORF54 is the sole viral protein responsible for IFNAR1 degradation during viral infection." (PMID 21998588, 2011).
breast cancer (291 papers, 1995 to 2026). A primary or metastatic malignant neoplasm involving the breast. "STAT1 expression in breast cancer was associated with poor prognosis and CD68-positive macrophage infiltration." (PMID 39843434, 2025). "On the other hand, STAT1−/− is linked with breast cancer tumorigenesis, where the spontaneous formation of α-positive and α-negative estrogen receptors is amplified." (PMID 38675812, 2024). "In fact, phosphorylation of STAT1 (Tyr701) has been associated with advanced tumor stage and worse survival in premenopausal breast cancer patients." (PMID 38167507, 2024). "STAT1 deficiency (STAT1−/−) has emerged as a feature in the pathobiology of many cancers, including breast cancer, colorectal cancer, esophageal cancer, and lung cancer." (PMID 38675812, 2024). "MFGE8-L, the canonical variant, possessed the capability to trigger STAT1 phosphorylation and inhibit the motility and invasion of breast cancer cells, whereas splice switch to MFGE8-S was found loss-of-function for this tumor-suppressive role." (PMID 38995840, 2024). "Instead, the fact that PD-L1-induced activation of STAT3 and STAT1 requires, as a prerequisite, that PD-L1 will be N-linked glycosylated, provides novel perspectives to PD-L1-directed therapy in breast cancer patients." (PMID 37830552, 2023). "For example, it has been found that STAT1 signaling stimulated by CD95/Fas is associated with an increase in cancer stemness in breast cancer cell lines." (PMID 38022653, 2023). "Recent reports have demonstrated that high STAT1 mRNA levels in breast cancer tissues are associated with macrophage infiltration and poor prognosis." (PMID 35618021, 2022). "The increased accumulation of CD11b+Ly6G+ granulocytic cells has been associated with augmented metastasis in breast cancer and head and neck squamous cell carcinoma during STAT1 deficiency." (PMID 34299314, 2021). "To address this, we performed genome-wide RNA-sequencing (RNA-seq) analysis on control and STAT1-deficient breast cancer cells (MT864 and MT4788) following IFNγ stimulation." (PMID 34083537, 2021). "The pathway affected by Que treatment was the JAK/STAT1 signaling pathway and was associated with precancerous breast cancer, as shown by network pharmacology analysis." (PMID 34838003, 2021). "The expression levels of these genes are associated with breast cancer subtypes and gene STAT1 is known to transmit information from extracellular signals to the cell nucleus." (PMID 32164570, 2020). "Knockdown of STAT1 in cancer-associated fibroblast co-cultured with human breast cancer cells altered cancer cell proliferation and delayed early breast cancer progression." (PMID 30237810, 2018). "In conclusion, JUN, FOS, ATF3 and STAT1 have been reported to be associated with breast cancer invasion and directly or indirectly participate in ECM remodeling." (PMID 30237810, 2018). "Their ER+ luminal phenotype, which is the most common phenotype in human breast cancers and the most common phenotype associated with advanced age, occurs only in Stat1 KO on the 129 background, implying there are genetic modifiers of this phenotype." (PMID 28865492, 2017). "Histological assessment of the mammary glands injected with MT/ShcA+/+ breast cancer cells and their corresponding STAT1- or STAT3-deficient counterparts revealed the presence of microscopic lesions in ∼40% of the mammary glands at necropsy." (PMID 28276425, 2017). "STAT1 deficiency ablates IFNγ-stimulated PD-L1 levels in MT/ShcA+/+ and MT/Shc313F/313F breast cancer cells." (PMID 28276425, 2017). "This is further supported by our observation in primary human breast cancers that elevated STAT1 transcriptional responses are only associated with enhanced PD-L1 expression levels in tumours that possess a low STAT3 transcriptional signature." (PMID 28276425, 2017). "Activation of the IFN/STAT1 pathway is closely associated with drug response and recurrence of breast cancer treated by chemotherapy." (PMID 27791205, 2016).
breast cancer (continued). "Two laboratories used C.129S6(Cg)-Stat1tm1Dlv mice bearing the Stat1-null allele backcrossed to the Balb/c strain to demonstrate that STAT1 functions as a mammary tumor suppressor." (PMID 26075897, 2015). "Consistently with this finding and the results of loss-of-function studies in mice, STAT1 expression is often lost in human breast cancer biopsies and STAT1 has been discussed as a predictive marker for breast cancer therapy." (PMID 24489749, 2014). "Of particular note, ER expression was strongly associated with cytoplasmic expression of STAT1 in primary breast cancers (p = 0.0003) and in the associated nodes (p = 0.005)." (PMID 24728078, 2014). "Decreased or loss of STAT1 expression has been observed in many types of cancer such as breast cancer, melanoma and leukemia." (PMID 25438156, 2014). "When these data are taken together, the lowest level of STAT1 expression is preferentially associated with the ERα+ breast cancer subtype." (PMID 22264274, 2012). "By analogy with these findings, very recently, fulvestrant treatment was reported to down-regulate the progesterone receptor levels, monitored by PET in STAT1-deficient mammary tumors in mice, reflecting the response to endocrine therapy." (PMID 23236424, 2012). "The important findings of this study are that loss of STAT1 expression is a frequent event during the progression of human breast cancers and that loss of functional STAT1 in mice causes spontaneous development of mammary adenocarcinomas." (PMID 22264274, 2012). "Similar to the classic tumor suppressors, restoration of WT STAT1 in the STAT1-/- mammary tumor cells spontaneously causes tumor cell death." (PMID 22264274, 2012). "Recent work in mouse models of neu/ERBB2-induced breast cancer has underlined STAT1's tumor suppressive role." (PMID 22185785, 2011). "Loss of the STAT1 downstream transcription factor IRF1 has been reported in MIN cases of human breast cancer." (PMID 22185785, 2011). "The second report did not discriminate between the intrinsic and the immunological contribution of STAT1-deficiency but came nevertheless to the conclusion that Stat1−/− × ERBB2/neu mice develop mammary tumors significantly faster than control mice." (PMID 22185785, 2011). "The importance of STAT1 as a tumor suppressor was underlined by the finding that all Stat1+/+ mammary cancers had partially lost or down-regulated STAT1 protein expression." (PMID 22185785, 2011). "Earlier investigators showed that a novel interferon (IFN)-regulated breast cancer gene cluster, including the transcriptional regulator STAT1, was associated with somewhat better prognosis cases relative to other basal-like breast cancers." (PMID 20946665, 2010). "However, recent studies in breast cancer suggest that elevated STAT1 levels are associated with increased disease progression through the regulation of proinflammatory and immunosuppressive cytokines." (PMID 40732340, 2025). "Importantly, the JAK/STAT1 signaling that is induced upon cGAS-STING activation has been associated with response to treatment in patients with breast cancer, including response to immunotherapy or chemotherapy." (PMID 38167507, 2024). "Additionally, the infiltration of M1-polarized tumor-associated macrophages (TAMs - F4/80+, p-Stat1 (Y701)+) was increased in the combination therapy group, which is often correlated with improved survival and outcome in breast cancer patients 65–67." (PMID 39097623, 2024). "To determine whether hsa_circ_0086735-miR-1296-5p-STAT1 axis was associated with luminal breast cancer cell function or patients’ survival, we assessed cell proliferation, cell apoptosis, and patients’ overall survival." (PMID 37187897, 2023). "Elevated STAT1 levels are associated with therapeutic resistance in ER+ breast cancer cells." (PMID 36430510, 2022).
breast cancer (continued). "Extensive studies have indicated that the abnormal regulation of STATs, especially for STAT1/3/5, is closely associated with the progression of various tumors, including solid tumors and hematologic malignancies, such as prostate cancer, breast cancer, CRC, and leukemias." (PMID 36061181, 2022). "Mutation of the S727 phosphorylation site of STAT1 (Stat1-S727A) increases the expression of perforin and granzyme B and enhances NK cell cytotoxicity in various tumor models, including for melanoma, leukemia, and metastasizing breast cancer." (PMID 34017344, 2021). "For example, two neo-adjuvant clinical trials, including palbociclib (CDK4/6i) plus endocrine therapy, showed that increased IFN/STAT1 signaling in ER+ breast cancers were associated with elevated immune checkpoint levels, endocrine resistance, and poor outcome." (PMID 33807608, 2021). "Nevertheless, the two STAT1-associated motifs revealed from this study suggested that the tumour microenvironment of Basal-like breast cancer composed of immune cells and understanding the roles of immune system in Basal-like pathogenesis will be the next challenge." (PMID 34161324, 2021). "In breast cancer, the loss of STAT1 in the mammary epithelium has been linked to neu-driven tumorigenesis and spontaneous breast tumor development in BALB/C mice, with the latter being associated with loss of epithelial IRF1 and impaired T cell infiltration and killing." (PMID 31842362, 2019). "STAT1 was associated with cancers, especially in breast cancers." (PMID 29796115, 2018). "Finally, selective loss of pY313-ShcA signalling exposes breast cancer cells to basally enhanced STAT1 and STAT3 signalling, to favour immune suppression." (PMID 28276425, 2017). "More recently, this simplified view on the role of STAT1 has been challenged by reports indicating that STAT1 up-regulation causes activation of genes which are associated with increased resistance of tumor cells to genotoxic stress and tumor growth in breast cancer." (PMID 28422713, 2017). "STAT1 induces apoptosis by up-regulation of caspases 2 and 3 expression and recently Magou and colleagues have reported a positive association between ph-STAT1 and caspase 3 expression in primary breast cancer tissues." (PMID 27769057, 2016). "Indeed, four separate groups have shown that Stat1-null mice have an increased susceptibility to mammary tumors in a variety of contexts." (PMID 26075897, 2015). "STAT3 inhibition might therefore be a useful single agent or combination therapy in breast cancer while STAT1 inhibition may be more intimately associated with endocrine treatment failure and a useful therapeutic strategy to target resistance." (PMID 24728078, 2014). "Our study reveals a complex association between STAT1 activation and progression of breast cancer." (PMID 24725474, 2014). "Thus, despite the significant association between the expression of IFN-γ and STAT1 transcripts in mammary tumors, the impact on tumor prognosis of these two parameters appears to be non-redundant." (PMID 24725474, 2014). "Our study confirms distinct prognostic relevance of STAT1 expression levels and STAT1 tyrosine phosphorylation in breast cancer patients and identifies an association of high STAT1 levels with elevated expression of STAT1 target genes and markers for infiltrating immune cells." (PMID 24725474, 2014). "In addition, Stat1-deficient mice can spontaneously develop estrogen receptor α-positive luminal mammary carcinomas." (PMID 23885756, 2013). "Here, we show that STAT1 expression is lost or significantly diminished in the neoplastic cells of a subset of human patients with ERα+/PR+ breast cancer relative to normal breast epithelium, suggesting that downregulation of STAT1 is associated with tumor progression." (PMID 22264274, 2012).